TMEM71 (transmembrane protein 71)
Synonyms: FLJ33069
Tractability: Antibody: UniProt predicts a signal peptide or a membrane-spanning region.
Gene: Protein-coding gene on chromosome 8 (132,685,007 to 132,760,712, reverse strand). Ensembl gene ENSG00000165071.
Subcellular location: Membrane
Subcellular location (Human Protein Atlas): Mitochondria
Gene Ontology:
Cellular component: mitochondrion; membrane
Genetic constraint (gnomAD): Loss-of-function variants: 38 observed, 32.84 expected, observed/expected ratio (o/e) 1.16, 90% interval 0.89 to 1.52. The upper end of that interval is the gene's LOEUF score, 1.52, which puts it in group 6 of 6, group 1 being the genes least tolerant of losing a copy. Missense variants: 326 observed, 325.72 expected, observed/expected ratio (o/e) 1, 90% interval 0.91 to 1.1. Synonymous variants: 116 observed, 115.45 expected, observed/expected ratio (o/e) 1, 90% interval 0.86 to 1.17.
Homologues: Orthologues: macaque TMEM71 (92% identical), chimpanzee TMEM71 (91% identical), pig TMEM71 (67% identical), rabbit TMEM71 (65% identical), mouse Tmem71 (65% identical), dog TMEM71 (64% identical), rat Tmem71 (63% identical), zebrafish tmem71 (28% identical).
Diseases named in the same sentence as TMEM71 in open-access papers:
TMEM71 is named in the same sentence as 12 diseases in open-access papers, as found by Europe PMC text mining. Sharing a sentence is not in itself a finding about the gene and the disease. The quoted sentences say what the papers report.
glioma (8 papers, 2019 to 2025). A benign or malignant brain and spinal cord tumor that arises from glial cells (astrocytes, oligodendrocytes, ependymal cells). "ST3GAL1 has been implicated in tumour progression and TMEM71 has been shown to be upregulated in gliomas." (PMID 36422592, 2022). "All these results indicate that TMEM71 expression was tightly associated with the development and malignancy progression of glioma." (PMID 31180187, 2019). "Of the seven signature CpG sites, only cg10054641 is a promoter CpG and regulates TMEM71 expression, which has been proven to be associated with malignancy and TMZ resistance in glioma." (PMID 35784470, 2022). "More importantly, high expression of TMEM71 was correlated with short survival time in both glioma and glioblastoma patients." (PMID 31180187, 2019). "Compared with age at diagnosis and tumor grade, the AUCs for TMEM71 expression level in the prediction of 3 years of survival in glioma were close to “grade” and higher than “age”." (PMID 31180187, 2019). "Further research revealed that TMEM71 expression was significantly higher in GBM than in lower‐grade glioma tissues." (PMID 31180187, 2019). "This indicates that revealing the mechanism of TMEM71 in glioma is essential for the treatment of this deadly disease." (PMID 31180187, 2019). "To further explore the molecular relevance between TMEM71 and glioma, we analyzed TMEM71 expression in different molecular subtypes." (PMID 31180187, 2019). "The results showed that the overall survival (OS) time of patients with higher TMEM71 expression in glioma is shorter than patients with lower TMEM71 expression." (PMID 31180187, 2019). "The results showed that TMEM71 was highly enriched in IDH‐wild‐type glioma and MGMT‐unmethylated glioma." (PMID 31180187, 2019). "Considering the significant biological heterogeneity between GBM and lower‐grade glioma, we additionally analyzed the prognostic value of TMEM71 in GBM patients from the two datasets." (PMID 31180187, 2019). "Also, there are some genes including coatomer protein complex subunit beta 2,50 transmembrane protein 71,51 and regulators of G protein singling 1652 which serve as prognostic factors via targeting glioma immunity." (PMID 33969928, 2021). "The TMEM71 expression level was also positively related to the histological grades of gliomas." (PMID 31180187, 2019). "The TMEM71 mRNA levels increased with increasing grades of glioma." (PMID 31180187, 2019). "The TMEM71 transcript levels were also increased significantly in mesenchymal subtype gliomas." (PMID 31180187, 2019). "Our study suggests that TMEM71 may function as an oncogene and serve as a new effective therapeutic target for the treatment of glioma." (PMID 31180187, 2019). "We focus on TMEM71, which has been hardly researched in glioma, even in tumors." (PMID 31180187, 2019). "These analyses indicate that TMEM71 might play a key role in the malignant progression of glioma." (PMID 31180187, 2019). "By examining the RNA sequencing data of glioma from the CGGA database, we found that the expression level of TMEM71 was positively correlated with tumor grade." (PMID 31180187, 2019). "Compared with lower‐grade gliomas, WHO grade IV gliomas (glioblastoma) showed a higher TMEM71 expression in the CGGA database." (PMID 31180187, 2019). "Moreover, the results showed that high expression of TMEM71 was highly enriched in the IDH‐wild‐type, MGMT unmethylation, and mesenchymal‐phenotype gliomas." (PMID 31180187, 2019).
breast carcinoma (4 papers, 2023 to 2025). "In parallel, emerging immune-metabolic regulators such as IL27RA and TMEM71 have been identified through single-cell and integrative transcriptomic analyses as potential prognostic and therapeutic indicators in breast cancer." (PMID 41398603, 2025).
asthma (1 paper, 2024). "However, the TMEM71 asthma DEG remained largely unchanged when adjusting for methylation at cg27159719." (PMID 38806494, 2024). "Testing for differential DNAm by asthma status, we found only five of these CpGs to be DMCs (i.e. significant for asthma at the Bonferroni level of p < 0.05/915): two CpGs for FKBP5 (cg03546163, cg23416081), two for TREML2 (cg26928682, cg18297196) and one for TMEM71 (cg27159719)." (PMID 38806494, 2024).
tumor (4 papers, 2019 to 2025). "TMEM71 was tightly associated with the immune and inflammatory response, cell proliferation, and cell migration, which are key steps for tumor progression." (PMID 31180187, 2019). "Recognizing the tumor microenvironment's critical role in cancer progression, we also explored the relationship between TMEM71 and immune cell infiltration using the ssGSEA algorithm." (PMID 39951856, 2025). "Local analysis confirmed that positive TMEM71 expression in tumor serves as an independent prognostic marker for NPC (HR = 0.53, 95% CI 0.366‒0.780)." (PMID 39951856, 2025). "Multivariate Cox regression analyses confirmed that positive TMEM71 expression in tumor tissues serves as an independent prognostic factor for NPC." (PMID 39951856, 2025). "Although our study is the first to reveal the anti-tumor role of TMEM71 in NPC, several limitations exist." (PMID 39951856, 2025). "Our study marks the first to outline TMEM71's tumor-suppressive impact in NPC, establishing its positive expression as a standalone protective factor for overall survival." (PMID 39951856, 2025). "Additionally, multiplex immunofluorescence staining revealed co-localization of TMEM71 with NLRP3 in NPC tumor cells." (PMID 39951856, 2025). "Molecular docking and co-immunoprecipitation validated the interaction between TMEM71 and NLRP3, while multiplex immunofluorescence showed co-localization of these proteins in tumor cells." (PMID 39951856, 2025). "TMEM71, identified in the GSE64634 and GSE102349 datasets, was downregulated in tumor tissues and positively correlated with NLRP3 expression." (PMID 39951856, 2025). "IHC analysis showed representative images of both positive and negative TMEM71 expression in NPC tumor tissues." (PMID 39951856, 2025).
cancer (2 papers, 2019 to 2025). A tumor composed of atypical neoplastic, often pleomorphic cells that invade other tissues. "The role of TMEM71 in various cancers is garnering attention." (PMID 39951856, 2025).
infection (1 paper, 2024). The state of being infected such as from the introduction of a foreign agent such as serum, vaccine, antigenic substance or organism. "Similarly to the present study, these authors observed increased TMEM71 expression (2.5-, 8.7-, and 35.8-fold increases respectively after 24, 48, and 72 hours of infection) and PKD1L2 (2.8-, 9.6-, and 49.9-fold increases at 24, 48, and 72 after infection, respectively)." (PMID 38512822, 2024).
TMEM71 also shares sentences with these, for which no sentence is quoted: glioblastoma (3 papers); gastric cancer (1); metastatic disease (1); nasopharyngeal carcinoma (1); ovarian carcinoma (1); papillary renal cell carcinoma (1).